RNF167 (ring finger protein 167)
Description:
E3 ubiquitin-protein ligase that acts as a regulator of the TORC1 signaling pathway. Positively regulates the TORC1 signaling pathway independently of arginine levels: acts by catalyzing 'Lys-29'-polyubiquitination and degradation of CASTOR1, releasing the GATOR2 complex from CASTOR1. Also negatively regulates the TORC1 signaling pathway in response to leucine deprivation: acts by mediating 'Lys-63'-linked polyubiquitination of SESN2, promoting SESN2-interaction with the GATOR2 complex. Also involved in protein trafficking and localization. Acts as a regulator of synaptic transmission by mediating ubiquitination and degradation of AMPAR receptor GluA2/GRIA2. Does not catalyze ubiquitination of GluA1/GRIA1. Also acts as a regulator of the recycling endosome pathway by mediating ubiquitination of VAMP3. Regulates lysosome positioning by catalyzing ubiquitination and degradation of ARL8B. Plays a role in growth regulation involved in G1/S transition by mediating, possibly by mediating ubiquitination of SLC22A18. Acts with a limited set of E2 enzymes, such as UBE2D1 and UBE2N.
Synonyms: RING105; LP2254; DKFZP566H073; 5730408C10Rik
Tractability: Antibody: UniProt places it where antibodies can reach, with high confidence; UniProt predicts a signal peptide or a membrane-spanning region; its Gene Ontology location is reachable by antibodies, with medium confidence. PROTAC: UniProt records ubiquitination sites on it; ubiquitination databases record sites on it; its protein half-life has been measured.
Gene: Protein-coding gene on chromosome 17 (4,939,997 to 4,945,222, forward strand). Ensembl gene ENSG00000108523.
Subcellular location: Lysosome membrane; Endosome membrane; Endomembrane system; Cell membrane; Lysosome membrane (Isoform 1); Cytoplasm, cytosol (Isoform 2)
Subcellular location (Human Protein Atlas): Cytosol; Vesicles; Centriolar satellite; Mitotic spindle
Gene Ontology:
Molecular function: protein binding; ubiquitin protein ligase activity; ubiquitin-protein transferase activity; zinc ion binding
Biological process: cellular response to leucine starvation; lysosome localization; negative regulation of cell cycle; negative regulation of TORC1 signaling; organelle localization; positive regulation of TORC1 signaling; protein K29-linked ubiquitination; protein K63-linked ubiquitination; protein polyubiquitination; regulation of synaptic transmission, glutamatergic; ubiquitin-dependent protein catabolic process; negative regulation of intracellular signal transduction; protein ubiquitination
Cellular component: cytoplasm; endolysosome membrane; endomembrane system; endosome; endosome membrane; lysosomal membrane; lysosome; plasma membrane; cytosol
Genetic constraint (gnomAD): Loss-of-function variants: 22 observed, 40.23 expected, observed/expected ratio (o/e) 0.55, 90% interval 0.39 to 0.78. The upper end of that interval is the gene's LOEUF score, 0.78, which puts it in group 3 of 6, group 1 being the genes least tolerant of losing a copy. Missense variants: 464 observed, 469.45 expected, observed/expected ratio (o/e) 0.99, 90% interval 0.92 to 1.07. Synonymous variants: 200 observed, 179.34 expected, observed/expected ratio (o/e) 1.12, 90% interval 0.99 to 1.25.
Homologues: Orthologues: chimpanzee RNF167 (99% identical), macaque RNF167 (98% identical), rabbit RNF167 (96% identical), pig RNF167 (94% identical), guinea pig RNF167 (93% identical), mouse Rnf167 (92% identical), rat Rnf167 (92% identical). Paralogues in human: RNF13 (48% identical), ZNRF4 (36% identical), RNF130 (22% identical), RNF150 (22% identical), RNF133 (21% identical), RNF149 (21% identical), RNF128 (20% identical), RNF148 (16% identical), RNF215 (13% identical).
Diseases named in the same sentence as RNF167 in open-access papers:
RNF167 is named in the same sentence as 22 diseases in open-access papers, as found by Europe PMC text mining. Sharing a sentence is not in itself a finding about the gene and the disease. The quoted sentences say what the papers report.
breast carcinoma (4 papers, 2021 to 2024). "Recent studies have demonstrated that ring finger protein 167 (RNF167) activates mTORC1 and promotes the occurrence of breast cancer by targeting and degrading K29-linked ubiquitinated cytosolic arginine sensor for mTORC1 subunit 1 (CASTOR1)." (PMID 39048965, 2024). "Together these results indicated that, similar to 293T cells, the CASTOR1 protein level was also regulated by AKT and RNF167 in breast cancer cells." (PMID 33594058, 2021). "To examine the importance of AKT1-mediated phosphorylation and RNF167-mediated degradation of CASTOR1 in breast cancer cells, we overexpressed Flag-CASTOR1 WT, S14A, and S14D in HCC1569, MCF7, and T47D cells." (PMID 33594058, 2021). "Taken together, these results revealed that AKT-mediated phosphorylation and RNF167-dependent ubiquitination led to a decreased CASTOR1 protein level in breast cancer cells, resulting in enhanced mTORC1 activation, cell proliferation, and tumorigenesis." (PMID 33594058, 2021). "RNF167 inhibited the activity of mTORC1 by regulating the Lys-63-linked and Lys-29-linked ubiquitination of SESN2 and CASTOR1, which played a significant tumor-suppressive role in colon and breast cancer." (PMID 38304253, 2023). "In vivo, high expression of RNF167 in breast tumors correlates with poor survival in human epidermal growth factor receptor 2 positive (HER2+) breast cancer while lower CASTOR1 expression was correlated with poor survival in estrogen receptor-positive (ER+) breast cancer." (PMID 35159190, 2022). "In addition, this observation confirmed that RNF167 is a therapeutic target of breast cancer." (PMID 39048965, 2024). "In this study, we report that a low expression level of CASTOR1 is correlated with poor patient survival in numerous types of cancer including breast cancer and that CASTOR1 is a substrate of RNF167." (PMID 33594058, 2021). "Furthermore, a lower CASTOR1 expression level and a higher RNF167 expression level were correlated with poor survival in ER+ and HER2+ breast cancer, respectively." (PMID 33594058, 2021). "Significantly, AKT and RNF167-mediated CASTOR1 degradation activates mTORC1 independent of arginine and promotes breast cancer progression." (PMID 33594058, 2021).
breast tumors (1 paper, 2021). "We found a high RNF167 expression level in breast tumors compared to the adjacent normal tissues." (PMID 33594058, 2021).
diabetes (1 paper, 2023). "The reduced expression of LMP2 and LMP7, along with increased RNF167 expression, may contribute to the future cardiac deterioration commonly observed in diabetes." (PMID 37895057, 2023).
diabetic cardiomyopathy (1 paper, 2023). Diabetic cardiomyopathy is a disorder of the heart muscle in people with diabetes. "Consistent with earlier reports on the role of the E3 ligases in regulating cardiac apoptosis, metabolism, hypertrophy, ischemia and diabetic cardiomyopathy, we found that the mRNA levels of the E3 ligase RNF167 were up-regulated in both Young and Adult db/db mice." (PMID 37895057, 2023).
hepatoblastoma (1 paper, 2020). Hepatoblastoma (HB) is a malignant hepatic tumor and is the most common pediatric liver cancer. "Rnf167, or Ring105, is an E3 ubiquitin ligase, and along with UbcH6 regulates the tumor suppressor TSSC5 in Wilms’ tumor, rhabdomyosarcoma, and hepatoblastoma." (PMID 32842712, 2020).
tumor (4 papers, 2020 to 2023). "Overall, these studies suggest that PA domain variants of RNF167 found in tumor samples are mislocalized and might act as dominant negatives." (PMID 35159190, 2022). "In addition to the identification of the RNF13 variants in tumor samples, some RNF167 variants were identified and characterized as well." (PMID 35159190, 2022). "However, these same studies highlight the importance of further investigating the function and the Ub ligase activity of tumor-associated RNF167 variants." (PMID 35159190, 2022). "In an early study, it was reported that RNF167 polyubiquitinates Tumor-Suppressing Subchromosomal Transferable Fragment cDNA (TSSC5), a tumor suppressor, to degrade it via the proteasome pathway." (PMID 35159190, 2022).
cancer (2 papers, 2021 to 2022). A tumor composed of atypical neoplastic, often pleomorphic cells that invade other tissues. "While the exact function of RNF167 in TSSC5 regulation is far from being understood, another study implicates RNF167 in cancer through the mammalian target of rapamycin complex 1 (mTORC1)." (PMID 35159190, 2022). "For instance, hundreds of single-nucleotide variation (SNV) mutations for RNF167, RNF13, and ZNRF4 have been reported in cancer." (PMID 35159190, 2022). "Altogether, these important studies provided some mechanistic insight regarding RNF167 dysfunction in cancer cells." (PMID 35159190, 2022). "The fact that a low mRNA expression level of CASTOR1 and a high mRNA level of RNF167 predict a poor prognosis of these cancer types suggest the existence of an additional mechanism(s) regulating their mRNA expression." (PMID 33594058, 2021). "Pharmacological intervention of RNF167 leading to CASTOR1 activation could be considered as a potential therapeutic approach for these cancer types." (PMID 33594058, 2021). "Importantly, a lower mRNA expression level of RNF167 predicts a poor prognosis in 6 of these 10 types of cancer." (PMID 33594058, 2021).
RNF167 also shares sentences with these, for which no sentence is quoted: acute myeloid leukemia (1 paper); breast invasive carcinoma (1); cervical squamous cell carcinoma (1); colorectal cancer (1); endocervical adenocarcinoma (1); gastric cancer (1); glioblastoma multiforme (1); GM2 gangliosidosis (1); head and neck squamous cell carcinoma (1); ischemia (1); lung adenocarcinoma (1); pancreatic adenocarcinoma (1); rhabdomyosarcoma (1); skin cutaneous melanoma (1); Wilms tumor (1).